CRP (C-reactive protein)
Diseases named in the same sentence as CRP in open-access papers (continued):
Sharing a sentence is not in itself a finding about the gene and the disease.
Stroke (continued). "Subsequent studies have investigated whether CRP levels after an initial ischemic event predict the risk of a second event, in patients with diverse stroke etiologies, measuring CRP at different times after stroke and with different follow-up times." (PMID 32733466, 2020). "Systemic inflammation, reflected by increased plasma concentrations of C-reactive protein (CRP) and fibrinogen, is associated with increased risk of coronary heart disease, but its relevance for stroke types remains unclear." (PMID 32221345, 2020). "The development of ultrasensitive ELISA or particle-enhanced techniques has allowed the detection limits of CRP concentration (hs-CRP) to be less than 0.3 mg/L Unlike CRP, hs-CRP is typically recognized as an indicator of upcoming stroke, peripheral vascular disease and acute myocardial infarction." (PMID 33256656, 2020). "This study also did not detect serum markers that can reflect the risk of stroke, such as D-dimer, C reactive protein, and brain natriuretic peptide." (PMID 32915163, 2020). "Similarly, serum CRP level above 4.3 mg/L was related to higher depressive symptoms 3 months after stroke (OR: 2.14, 95%CI: 1.33–3.44, P < 0.01)." (PMID 31996746, 2020). "Interestingly, CRP was measured at different times after stroke in different studies, either in the early hours after stroke or between 7 days and 3–6 months from onset." (PMID 32733466, 2020). "Moreover, elevated blood CRP levels have been reported to correlate with the severity of neurological deficits to form and the mortality after stroke." (PMID 30720741, 2019). "A significantly higher discriminating capacity was still observed for FABP4 to predict stroke recurrence (AUC, 0.75; 95% CI, 0.70–0.81), compared to Hs-CRP (AUC 0.70; 95% CI, 0.62–0.76; P=0.009), HCY (AUC 0.71; 95% CI, 0.63–0.78; P=0.01) and NIHSS score (AUC 0.77; 95% CI, 0.70–0.83; P=0.09)." (PMID 30969942, 2019). "Furthermore, CRP also induces the release of monocyte tissue factor, contribute to plaque rupture and acute thrombotic events such as myocardial infarction and stroke." (PMID 31814936, 2019). "In addition, NIHSS score on admission and Hs‐CRP were independent factors to predict stroke outcomes." (PMID 31397082, 2019). "Acute CRP was higher in patients with severe stroke compared to those with mild stroke." (PMID 31345181, 2019). "CRP elevation may reflect a systemic inflammatory response following ischemic stroke, the degree of stroke severity, or concurrent infections at the time of sampling." (PMID 30718369, 2019). "CRP is a well-known predictive marker for myocardial infarction and stroke in healthy subjects." (PMID 31777503, 2019). "CRP levels were significantly associated with incident stroke and ischemic stroke, but not with ICH." (PMID 30254628, 2018). "In dialysis patients, C-reactive protein (CRP) is predictive of stroke and death." (PMID 30037144, 2018). "Copenhagen City Heart Study showed that high baseline plasma YKL-40 was significantly associated with incident-stroke, independent of hs-CRP, but not with myocardial infarction." (PMID 29686891, 2018). "Furthermore, serum neopterin independently predicted PSD occurrence after 6 months of stroke onset (OR:1.95, 95% CI:1.36–2.81) and demonstrated a prominently higher discriminatory ability when compared to Hs-CRP." (PMID 30061860, 2018). "Since B2M levels correlate with CRP, TNF-α, IL-6, and cardiovascular risk factors in hemodialysis patients, this UT could possibly increase the risk of stroke by acting on inflammation." (PMID 30037144, 2018). "IL-1, IL-6, TNF-α, and C-reactive protein (CRP) are potential targets of stroke therapy." (PMID 29382106, 2018). "The inflammatory cytokines of CRS, such as interleukin-1 and C-reactive protein, are also speculated to play a role in the development of stroke." (PMID 29494700, 2018). "A cross-sectional survey was carried out among 103 conveniently selected stroke patients who attended CRP between December 2015 and May 2016." (PMID 29078803, 2017).
Stroke (continued). "In this retrospective study we confirm that body temperature elevation within 48 h of stroke onset is common and associated with neurological status at admission (NIHSS score), female gender, swallowing difficulties, intubation and CRP > 50 or signs of infection at admission." (PMID 29237408, 2017). "CRP is one of the few centres available for stroke rehabilitation." (PMID 29078803, 2017). "A cross-sectional study of stroke patients who attended CRP for rehabilitation services was conducted between December 2015 and May 2016." (PMID 29078803, 2017). "Finally, the most relevant criteria that emerge to characterize stroke due to pancreatic cancer are as follows: a radiological pattern 4, a high D-dimer and CRP level, and an elevated prothrombin time." (PMID 27368015, 2016). "Further adjustment for CVD risk factors including smoking, physical activity, social class, BMI, HDL-C, systolic BP, antihypertensive treatment, eGFR, prevalent MI, prevalent stroke, CRP, HOMA-IR and blood glucose (Model 2) attenuated the association, although it remained statistically significant." (PMID 27312697, 2016). "CRP is reported to be related to poor prognosis after stroke." (PMID 27375741, 2016). "Hs-CRP reflected the level of inflammatory response after stroke." (PMID 27699084, 2016). "Therefore, this study is conducted to compare the hs-CRP levels and lipid profile parameters between stroke patients and control group and demonstrate correlation between biomarkers with neurological deficit or short term outcome." (PMID 27648176, 2016). "Previous studies indicated that CRP is a strong but nonspecific risk factor of fatal stroke in elder Europeans and that the increased level of CRP is associated with a worse outcome in patients with ischemic stroke." (PMID 27164124, 2016). "Third, the timing of sampling in relation to stroke onset may have impacted our findings; further prospective studies of the optimal timing of CRP measurement for use as a prognostic marker after ischemic stroke are warranted." (PMID 27555819, 2016). "There is insufficient evidence for the association between CRP and PSF in stroke patients." (PMID 26599129, 2015). "We hypothesized that early levels of the inflammatory and anti-inflammatory markers LBP, IL-10, IL-6 and CRP are biomarker candidates for the prediction of post-stroke infections in acute ischemic stroke patients." (PMID 25613713, 2015). "We found a weak but significant cross-sectional association between CRP levels and fatigue scores at six months after stroke, but this association was not significant at either one month or 12 months." (PMID 26599129, 2015). "The adjusted hazard ratio (HR) per two-fold higher CRP concentration for all deaths was 1.29 (1.10-1.52), and after excluding PD-unrelated deaths, such as cancer or stroke, HR was 1.23 (1.01-1.49) (adjusted for age, sex, PD duration, modified Hohen-Yahr stages, MMSE scores, and serum albumin)." (PMID 26218286, 2015). "Besides, in our study, PCOS group showed higher levels of CRP level and BMI that have been known as risk factors for cardiovascular disease ( CVD ), leading to elevated risk of CVD and/or stroke in this population." (PMID 25918586, 2015). "This may be explained by the findings from a longitudinal study that most observed inflammatory biomarkers (including CRP) decreased significantly by one year after stroke." (PMID 26599129, 2015). "Plasma Ox-LDL may be a more powerful predictor than serum LDL, high-sensitivity C-reactive protein or white blood cell counts for stroke outcome." (PMID 24423248, 2014). "In one study where serum CRP was measured within 24 h after stroke onset, within 48–72 h and at hospital discharge, persistently normal values were seen in 19.5 % of patients, increasing values in 6.3 %, decreasing values in 28.1 %, and persistent elevation in 46.1 %." (PMID 24531853, 2014).
Stroke (continued). "Baseline level of CRP is a strong independent predictor of the risk of future myocardial infarction, peripheral vascular disease, stroke, and vascular death among healthy individuals without known vascular disease." (PMID 24991087, 2014). "In a Japanese retrospective study, elevated CRP concentrations were associated with higher incidence of all stroke and IS, but not heamorrhagic stroke." (PMID 25191699, 2014). "Subgroup analyses showed that higher hs-CRP concentration was more prone to be a risk factor for all stroke and IS in non-fatal stroke, male and hypertensive participants." (PMID 25191699, 2014). "Elevated serum C-reactive protein (CRP) level is a marker for increased systemic inflammation and is associated with both macrovascular [i.e stroke and coronary heart disease (CHD)] and microvascular [i.e diabetic nephropathy and chronic kidney disease (CKD)] disease." (PMID 23844046, 2013). "Accordingly, CRP in blood can reflect the process involved with inflammation and it is a strong independent predictor of future peripheral arterial disease, myocardial infarction, and stroke among apparently healthy men and women." (PMID 23484158, 2013). "Recently, it has been shown that patients with elevated CRP and receiving rosovastatin had 48% reduction in stroke prevalence, 46% reduction in the need for intervention to reopen blocked blood vessels, and a 20% reduction in all-cause mortality (JUPITER Trial)." (PMID 23924883, 2013). "Nonetheless, in secondary prevention of stroke, elevated CRP adds to current prognostic markers, although it remains to be established whether specific therapeutic options can be derived from this." (PMID 24353532, 2013). "Cocaine abusers had fivefold to sixfold increases in the levels of CRP, which lead to sudden heart attack and may also trigger fatal cardiovascular events such as strokes." (PMID 24044608, 2013). "Correlation of YKL-40 and CRP Levels with Stroke Severity, Infarct volume, and Functional Outcome." (PMID 23272150, 2012). "Ongoing inflammation eventually damages the arteries: it is so closely associated with heart disease that a test for inflammation called CRP (C-reactive protein) is used to assess cardiovascular risk, predicting the risk of Coronary Heart Disease (CHD) and stroke, together with cholesterol levels." (PMID 22690145, 2012). "The relation to stroke risk was not affected by adjustment for covariates, including C-reactive protein." (PMID 21283828, 2011). "In a small, preliminary study, patients at risk of stroke (multiple risk factors for stroke, with chronically elevated C-reactive protein, but negative MRI for brain pathology) exhibited increased inflammation in the brain, as indicated by PET imaging." (PMID 21356305, 2011). "Concurrent infections are common in stroke victims and will affect the blood CRP level." (PMID 22389829, 2011). "The observed relations were of modest magnitude, and the relations of TIMP-1 to stroke risk were not explained to any major extent by established cardiovascular disease risk factors or C-reactive protein." (PMID 21283828, 2011). "We previously showed that the burden of Chlamydia pneumoniae in carotid plaques was significantly associated with plaque interleukin (IL)-6, and serum IL-6 and C-reactive protein (CRP), suggesting that infected plaques contribute to systemic inflammatory markers in patients with stroke risk." (PMID 20543948, 2010). "Additionally, BMI (p<0.001) and a history of stroke (p=0.012) were shown to affect the hs-CRP levels." (PMID 21203342, 2010). "The prognostic significance of early CRP after stroke has significant clinical implications." (PMID 19400931, 2009). "CRP level after the acute phase of stroke, however, is confounded by many factors including index stroke severity, co-existing infections, stress and complications of stroke such as deep vein thrombosis." (PMID 19400931, 2009).
Stroke (continued). "It remains to be seen whether CRP is a marker of stroke severity, or is a response to stroke, or a mixture of both." (PMID 19400931, 2009). "After adjusting for the effect of confounding factors, high CRP remained to be associated with more severe stroke and high mortality, but not with functional outcome or etiology." (PMID 19400931, 2009). "The results show that IL-6, CRP, and to a lesser extent, fibrinogen are more closely linked to risk of fatal MI or stroke (i.e., fatal CVD) than to nonfatal vascular events in the elderly at risk." (PMID 19554082, 2009). "In addition, only few studies have analyzed the relationship between elevated admission CRP levels and stroke severity or stroke etiology." (PMID 19400931, 2009). "The Rotterdam study shows that although high CRP is associated with the risk for future stroke, it is not useful for individual stroke prediction." (PMID 19400931, 2009). "Elevated levels of serum C-reactive protein (CRP), a non-specific marker of inflammation, predict cardiovascular disease and dementia, and have been associated with stroke patients." (PMID 15476562, 2004). "Furthermore, a randomized double-blind trial demonstrated that individuals with elevated CRP levels had a 4.7-fold increased risk of recurrent stroke compared to those without elevated CRP." (PMID 40491586, 2025). "Additionally, cystatin C activates inflammatory pathways (e.g., NF-κB) and promotes the release of pro-inflammatory cytokines (e.g., IL-6, CRP), establishing a vicious cycle of post-stroke neuroinflammation and delayed neuronal death, significantly increasing all-cause mortality." (PMID 40941489, 2025). "Factors identified that may be used to predict intracerebral hemorrhage-associated pneumonia include older age, National Institutes of Health Stroke Scale (NIHSS), dysphagia, patients with coma, pre-stroke modified Rankin Scale (mRS), C-reactive protein levels, serum urea, cognitive impairment, etc." (PMID 39977414, 2025). "However, exploratory correlation analysis suggests a link between NETs and inflammation following EVT alone with stroke severity and long-term functional outcomes, as demonstrated by the positive correlation of CitH3 and CRP with NIHSS scores at 24 h and mRS scores at 90 days." (PMID 40571868, 2025). "The clinical and radiological outcomes observed in this population, as well as their association with CRP levels, may not be directly applicable to other stroke subtypes, such as small vessel occlusion, or to patients who did not receive EVT." (PMID 40682467, 2025). "Their ability to lower C-reactive protein (CRP) provides a biomarker-based link between statin exposure and anti-inflammatory benefit, suggesting mechanisms that could explain mortality and cognitive protection across diverse stroke subtypes." (PMID 41295435, 2025). "Therefore, in the current study, we assessed the association between baseline CRP levels and outcomes in patients with EVT-treated LVO stroke and determined whether this effect differed across subgroups according to stroke etiology." (PMID 40682467, 2025). "It is therefore understandable that stroke patients with cancer mostly presented with heightened coagulation activity, principally raised D-dimer, fibrinogen monomer, and fibrinogen, along with inflammatory markers such as elevated C-reactive protein (CRP) levels." (PMID 40351898, 2025). "In addition, the mediating effect results showed that CRP could act as a mediator between METS-IR and stroke risk, and UA and stroke risk, with mediation ratios of 9.01% and 26.34%, respectively." (PMID 39634177, 2024). "Overall, stroke patients were more likely to be older and smokers, and had higher BMI, blood glucose, total cholesterol, total triglycerides, low density lipoprotein cholesterol, and CRP as well as lower levels of high density lipoprotein cholesterol compared with non-stroke participants (P < 0.05)." (PMID 39634177, 2024).
Stroke (continued). "Also, T12MI was negatively correlated with CRP in patients with stroke and AP." (PMID 39666645, 2024). "The predictive ability of NT-proBNP for coronary artery disease and stroke was greater than high-density lipoprotein cholesterol or C-reactive protein, and NT-proBNP could serve as a multipurpose biomarker in new approaches that integrate HF into CVD primary prevention." (PMID 39767625, 2024). "In our discovery cohorts, Duffy-null status appeared to be associated with a higher risk of all-cause mortality and incident stroke, though these associations were attenuated and non-significant following adjustment for traditional risk factors including hs-CRP." (PMID 39596582, 2024). "Lymphopenia, elevated levels of C-reactive protein (CRP), interleukins (IL-6 and IL-2R), lactate dehydrogenase (LDH), ferritin, markers of hepatic function, and troponins are associated with adverse outcomes such as acute myocardial infarction, venous thromboembolism, and stroke." (PMID 39066303, 2024). "Therefore, the results of mediation analyses of CRP as an inflammatory marker suggest that METS-IR and UA levels may affect stroke risk by influencing the level of inflammation and degree of oxidative stress." (PMID 39634177, 2024). "Regardless of the exact mechanism of CRP elevation, it associates with general stroke and CVD risk." (PMID 38732147, 2024). "A possible factor is an increase in C reactive protein concentrations, which could promote atherosclerotic plaque instability, making the plaque more likely to rupture and lead to thrombotic events such as heart attacks or strokes." (PMID 39603704, 2024). "Furthermore, previous studies have demonstrated that HGS weakness was associated with increased level of inflammatory factors, such as C-reactive protein and interleukin-6, which in turn could contribute to a heightened vulnerability to stroke incidence." (PMID 37908684, 2023). "However, CRP was not specific for stroke and was also associated with deaths from cancer, lung disease and non-vascular causes." (PMID 41541100, 2023). "Region-based subgroup analysis demonstrated that there was a poor correlation between hs-CRP levels and recurrent stroke whether in the subgroup of Asia [RR = 1.02, 95% CI (1.00 ~ 1.04); p = 0.017] and the subgroup of non-Asian regions [RR = 1.03, 95% CI (1.01 ~ 1.05), p = 0.002]." (PMID 37342777, 2023). "Given its importance, the absence of CRP data in our study may potentially impact affect the comprehensive analysis of stroke risk." (PMID 38028467, 2023). "Nevertheless, CRP, due to its stability and ease of measurement, remains an attractive biomarker to stratify risk of recurrent stroke or vascular events including fatal and non-fatal post-stroke myocardial infarction." (PMID 41541100, 2023). "The results from this large multicenter cohort study indicate that increased CRP levels during the first 24 h of hospitalization for ischemic stroke were associated with the occurrence of early cardiac complications, suggesting that CRP may be a possible biomarker for stroke–heart syndrome." (PMID 37119383, 2023). "Second, per unit increase in hs-CRP levels was found to not be associated with poor prognosis and recurrent stroke after the trim-and-fill method was applied, calling for negative results to be reported in future research to avoid overestimating the clinical significance of hs-CRP." (PMID 37342777, 2023). "The evaluation of the study included the potential impact of SNPs of the CRP gene (rs1130864, rs1417938, rs1800947, rs3093077) as well as CRP plasma level on a combined CV endpoint (CV death, death from stroke, myocardial infarction (MI), and stroke/transient ischemic attack (TIA))." (PMID 37443809, 2023). "In patients with CRP levels 1–3 mg/L within the first 24 h of stroke, no significant increased risk of ischemic heart disease (HR 1.05, 95%CI 0.99–1.11) or Takotsubo cardiomyopathy (HR 0.95, 95%CI 0.53–1.71) was found when compared to those with CRP levels < 1 mg/L." (PMID 37119383, 2023).